INS (insulin)
Diseases named in the same sentence as INS in open-access papers (continued):
Sharing a sentence is not in itself a finding about the gene and the disease.
Hyperglycemia (continued). "However, for the majority of T2DM patients, including those in our study, the initial drug of choice for the management of hyperglycemia is OHA, followed by insulin in the event they fail to respond to OHA or if any side effects occur." (PMID 35227220, 2022). "We found sacubitril and valsartan, but surprisingly not their combination, improves insulin secretory dysfunction and reduces hyperglycemia in STZ-treated mice." (PMID 35733766, 2022). "This is in agreement with studies showing that teleosts respond to hyperglycemia by increasing insulin production, but the target tissue insulin action is not tightly regulated as in mammals." (PMID 36127383, 2022). "It is noteworthy that VSE patients, despite receiving more insulin, did not experience more frequent episodes of hyperglycemia." (PMID 35109925, 2022). "The symptoms at the early stages of this syndrome include hyperglycemia, hyperinsulinemia, and the impairment of glucose uptake in skeletal muscle cells, which are not sensitive to the insulin effect, or insulin resistant." (PMID 36552772, 2022). "The disease occurs when the pancreas does not produce enough insulin or when the body’s cells are insulin resistant, leading to hyperglycemia after meals." (PMID 35408706, 2022). "Moreover, secretion of GLP-1, a hormone that is secreted after meal ingestion and stimulates insulin secretion, has been observed after PD, with both, GLP-1 and hyperglycemia being known to delay gastric emptying." (PMID 35625491, 2022). "The β-cell changes found in diabetic βV59M mice are prevented by restoration of euglycaemia with insulin, indicating they are due to hyperglycaemia/hypoinsulinaemia not KATP channel activation per se2." (PMID 36376280, 2022). "Unlike insulin, glucose crosses the placenta, and, therefore, maternal hyperglycemia leads to intrauterine hyperglycemia and subsequently fetal hyperinsulinemia, which increases fetal growth." (PMID 35472047, 2022). "Retrospective CGM only allows retrospective evaluation and review of glucose readings and does not allow the patient to make changes to their insulin dose at the time of hyperglycemia." (PMID 36714590, 2022). "In our study, T2DM subjects were on medications to treat hyperglycemia (most commonly metformin, DPP-4 inhibitors, and basal insulin), hypertension (most commonly angiotensin-converting enzyme inhibitors or angiotensin II receptor blockers), and dyslipidemia (most commonly statins)." (PMID 35683611, 2022). "Although most of the patients with NASH are insulin resistant, they do not show hyperglycemia because of decreased ability of the liver to clear insulin." (PMID 35203540, 2022). "Strong correlations between the AL ratio and insulin levels have also been highlighted in Asian populations with and without hyperglycemia." (PMID 35654771, 2022). "Patients with high HGI use insulin to control blood sugar at a higher rate, indicating lack of capacity to control blood sugar well and the development of hyperglycemia, which negatively affected the function of various systems in the body." (PMID 36407464, 2022). "Inhibitors of this enzyme may cause beta mobile pressure to decrease (thus decreasing postmeal hyperglycemia) and the production of glucagon-like peptide-1 (GLP-1) to increase (thus increasing insulin secretion) as a result." (PMID 35586686, 2022). "Given that hyperglycemia was partially rescued by SFG supplementation, we assessed whether this benefit of SFG is dependent on gaining insulin sensitivity." (PMID 35893259, 2022). "Changes in insulin signalling and glucose tolerance involve hyperglycaemia (either after fasting or in non-fasted animals), lower insulin sensitivity, as well as higher insulin increment during glucose tolerance test (GTT)." (PMID 35197931, 2022).
Hyperglycemia (continued). "In this trial, infants who had received enhanced PN did so without increased metabolic complications such as hyperglycemia, hypertriglyceridemia, hyperbilirubinemia, or increased days of insulin use when compared to the control group." (PMID 36235546, 2022). "Between algorithm-based titration protocols, a higher degree of “stringency” (requesting greater increments in insulin doses per titration step with higher degrees of hyperglycemia) did not improve outcomes." (PMID 35942330, 2022). "GFAP expression was increased at 4 weeks of hyperglycemia but decreased at 8 weeks, and did not increase with insulin treatment." (PMID 36552776, 2022). "It was reported that administration of FTY720 to db/db mice led to sustained normalization of hyperglycemia by stimulating β‐cell in vivo regeneration without affecting the insulin sensitivity." (PMID 35064580, 2022). "Immune-mediated destruction of β-cells in pancreatic islets results in diminished or absent release of insulin and consequent hyperglycemia." (PMID 34441977, 2021). "An APS provides data including total insulin requirement to maintain BGL, average BGL, percent of hyperglycemia, target-in-range, or hypoglycemia during the experimental duration of 2–3 days, from which one can infer the general physiological state of a diabetic rat." (PMID 34270619, 2021). "To directly test if the suppression of insulin action is required for the heparin‐induced hyperglycaemia, we tested the inhibitory effects of heparin on muscle glucose uptake in mice with or without insulin treatment." (PMID 34277977, 2021). "DPP4 is a key factor that modulates postprandial hyperglycemia by degrading incretin peptides, i.e., glucagon‐like peptide 1 (GLP‐1) and glucose‐dependent insulinotropic polypeptide (GIP), which induce secretion of insulin from pancreatic β cells." (PMID 33006264, 2021). "KS patients develop hyperglycemia earlier in life than those without KS and show lower insulin sensitivity and higher insulin secretion." (PMID 34852815, 2021). "The insulin-producing cells can release insulin in a glucose-responsive manner and normalize hyperglycemia for a long period without immunosuppressive agents." (PMID 33541422, 2021). "Although results from experimental studies support a causal relationship between hyperglycemia and poor functional outcome after stroke, multicenter trial data presented in the SHINE, GIST-UK, or THIS trial do not yet support intervention with insulin." (PMID 34305796, 2021). "Despite the hyperglycaemia, the animals were in good general condition and the use of insulin was not required." (PMID 34072110, 2021). "An appropriate dose of rapid-acting insulin can be used to treat hyperglycemia after morning exercise of any type without inducing hypoglycemia post-exercise." (PMID 34501920, 2021). "The surviving pups displayed reduced weight and rapidly developed hyperglycemia due to severe lack of insulin." (PMID 34487921, 2021). "Yet, our studies suggest that beyond transient hyperglycemia, developmentally programmed heart disease is more complex as lipids and insulin, rather than just hyperglycemia, appear to play important roles." (PMID 33673574, 2021). "The use of basal insulin analogs in conjunction with regular insulin infusions may speed up the resolution of DKA and minimize rebound hyperglycemia events, resulting in less ICU length of stay and less healthcare cost." (PMID 36994324, 2021). "Additionally, insulin levels vary with T2DM duration and treatment, partly due to hyperglycemia, beta cell failure, and glucose-lowering medications." (PMID 33691751, 2021). "The recent Stroke Hyperglycemia Insulin Network Effort (SHINE) trial, performed in AIS patients with concomitant hyperglycemia, evaluated the impact of intensive versus standard insulin therapy during the first 72 h from symptom onset on a 90-day functional outcome." (PMID 34300171, 2021).
Hyperglycemia (continued). "It is characterized by a complete or partial lack of insulin secretion and/or insulin metabolism which results in chronic hyperglycemia." (PMID 33567628, 2021). "The authors conclude that hyperglycemia is a factor that significantly increases the length of hospital stay for exacerbation of asthma, regardless of the mode of insulin therapy." (PMID 33520042, 2021). "An early study on alloxan-induced T1DM in Wistar rats showed that intraperitoneally-injected C. pyrenoidosa swiftly counteracted hyperglycemia without affecting insulin secretion." (PMID 33572056, 2021). "Although the total amounts of secreted insulin and C-peptide during glucose stimulation in HFHSD-fed mice were increased, the levels of insulin were not sufficient to compensate for the hyperglycemia." (PMID 33670429, 2021). "In an insulin resistant state, free fatty acids increase as lipolysis is not suppressed and de novo lipogenesis occurs from hyperglycemia which helps in part to explain the sustained elevated TG observed in our study." (PMID 34544430, 2021). "For KS patients with hyperglycemia, we recommended individualized hypoglycemia drug selection after evaluating islet β-cell function rather than taking insulin therapy at first." (PMID 34852815, 2021). "Lack of insulin-induced nutrient uptake promotes hyperphagia, while hyperglycemia induces polyuria and ensuing polydipsia." (PMID 34504898, 2021). "This pathophysiological condition occurs when the pancreas does not secrete sufficient insulin or/and the body cannot effectively use insulin leading to hyperglycaemia." (PMID 34063700, 2021). "The absence or near-absence of endogenous insulin leads to hyperglycemia (high blood glucose), which must be treated by exogenous insulin, either through injections or an insulin pump." (PMID 34444464, 2021). "We included patients with abnormal or diabetic OGTT and on steroids in our study because our objective was to study the prevalence of hyperglycaemia during exacerbations in CF patients not on insulin, regardless of its aetiology." (PMID 33855211, 2021). "This impairs insulin secretion and glucose utilization, increases target organ resistance to insulin, and results in hyperglycemia even without surgical stress." (PMID 34659435, 2021). "A previous study revealed that hyperglycemia (12 mmol/L), regardless of the level of insulin, activated the coagulation cascade." (PMID 33859617, 2021). "Around the age of 8 months, both male and female KO mice had increased fasting glucose levels of around 180 mg/dl, and increased fasting serum insulin levels as compared with WT mice, indicating that IRF3 KO mice progressively develop hyperglycemia and hyperinsulinemia." (PMID 34091599, 2021). "To date, the US Food and Drug Administration (FDA) has not approved any medication to treat MetS; however, an insulin-sensitizing agent, such as metformin, is currently widely administered in patients with MetS at the start of hyperglycemia treatment." (PMID 33573121, 2021). "An effective method to decrease excess insulin exposure whilst simultaneously improving glucose homeostasis, for hyperinsulinaemia with or without hyperglycaemia, is through lifestyle management." (PMID 34572351, 2021). "The post-burn development of hyperglycaemia, insulin resistance or a hypermetabolic state did not change the majority (87.5%) of therapists’ exercise prescription." (PMID 33709001, 2021). "The majority of these children did not achieve glycaemic control and required insulin for management of their hyperglycaemia after 4‐5 years, indicating the need for increased awareness of T2DM and intensive treatment in this special group." (PMID 33855201, 2021). "In mice, RANKL seems to worsen insulin sensitivity, while the decoy receptor OPG, which physiologically antagonizes the activity of RANKL on osteoclast precursors, is able to delay the onset of hyperglycemia in diabetic animals." (PMID 33801212, 2021).
Hyperglycemia (continued). "In addition, β-cell dedifferentiation is a critical determinant of the change in insulin-to-glucagon ratio in hyperglucagonemia, in patients with T2DM contributing to uncontrolled hyperglycemia, which further can aggravate progression of T2DM." (PMID 34068827, 2021). "Deletion of Ngn3 or Neurod1 results in similar phenotypes, with postnatal pancreas lacking endocrine cells and mice dying of hyperglycemia due to a lack of insulin." (PMID 34943978, 2021). "This miRNA is expressed in insulin-secreting cells where it can inhibit the releasing of insulin by suppressing the expression of onecut-2 (OC2) transcription factor and subsequently up-regulation of granuphilin in hyperglycemia conditions." (PMID 33995938, 2021). "During the progression of IR, insulin fails to suppress hepatic glucose production, but paradoxically accelerates lipid synthesis, leading to hyperglycemia and hypertriglyceridemia." (PMID 34731089, 2021). "The participants in our study received the optimal treatment for hyperglycemia rather than intensive insulin infusion or regular sliding-scale insulin therapy." (PMID 34075142, 2021). "Future trials should consider initiating insulin therapy based on MHG rather than other hyperglycemia measures." (PMID 33420311, 2021). "Without an increase in exogenous insulin, however, hyperglycemia can persist for hours after brief, intense exercise in people with T1D." (PMID 34444464, 2021). "The analysis of mechanisms by which hyperglycaemia induces detrimental effects on ischemic myocardium suggests an early start of insulin treatment in non-diabetic patients with ACS and SIH at admission." (PMID 33466656, 2021). "Both type 1 (insulin dependent) and type 2 (non-insulin dependent) DM share the same feature, which is hyperglycemia that results from poor insulin action." (PMID 34769045, 2021). "However, in models of induced hyperglycemia (STZ) and glucose intolerance (HFD), ursolic acid has been shown to exert positive effects on circulating levels of insulin and glucose." (PMID 35098034, 2021). "Pharmacological inhibition of NOX4 in HFD-induced glucose-intolerant C57BL/6 mice counteracted non-fasting hyperglycemia and impaired glucose tolerance without any change in peripheral insulin sensitivity." (PMID 33893069, 2021). "Instead of monotherapy with RXR agonists, the combination treatment of RXR and PPARγ agonists was shown to be more effective in increasing insulin sensitization and reducing hyperglycemia in murine models of obesity and non-insulin-dependent diabetes mellitus." (PMID 34680110, 2021). "Administration of 25% glucose to metformin-pretreated mice induced hyperglycemia, but surprisingly did not reverse the benefits of metformin on hippocampal insulin signaling and fear memory following isoflurane anesthesia." (PMID 34512303, 2021). "Thus, hyperglycemia improves the action of the cytokine signaling suppressor (SOCS), altering the release of insulin and its signaling pathway." (PMID 33547367, 2021). "The pathological hyperglycemia and hyperinsulinemia in IGT may regulate the expression of microRNA-21 (miR-21) and affect the downstream insulin signaling pathways, leading to endothelial cell dysfunction and early renal damage." (PMID 33967958, 2021). "SARS-CoV-2 infects the pancreas through ACE2, being highly expressed there when compared to other organs, leading to pancreatic damage with subsequent impairment of insulin secretion and development of hyperglycemia even in non-DM patients." (PMID 34124187, 2021). "Because both hyperglycemia and hyperinsulinemia exist in patients in the IGT stage, we investigated the change in the expression of miR-21 in HGECs exposed to high concentrations of glucose and insulin in combination." (PMID 33967958, 2021).
Hyperglycemia (continued). "A decrease in the number of functional insulin-producing beta cells is the key factor in the development of T2DM and hyperglycemia, while dyslipidemia, cytokines, leptin, autoimmunity, and some sulfonylureas may contribute to the damage of beta cells." (PMID 33613101, 2021). "Soymorphin-5 inhibited hyperglycemia without increasing plasma insulin levels while decreasing plasma and liver TG levels and liver weight." (PMID 34445273, 2021). "The insulin sliding scale is an agent approved for use in diabetic patients; however, in older patients, it may have a higher risk of hypoglycemia without an improvement in hyperglycemia management, and it is now recommended to avoid using it in older adults as per the 2019 AGS Beers criteria." (PMID 34577544, 2021). "In the emergency department, we were using sliding scale insulin for patients with hyperglycemia; however, we did not measure the effect of exogenous insulin on the cytokine’s levels." (PMID 34117510, 2021). "Furthermore, a triterpene isolated from Viburnum odoratissimum has been reported to stimulate glucose absorption in insulin-resistant HEPG2 cells, thereby preventing hyperglycemia." (PMID 34885816, 2021). "Patients with hyperglycaemia in the group with IMV received insulin therapy more frequently than patients without VMI." (PMID 34277995, 2021). "Both hyperglycemia and TNF-α lead to impaired insulin signaling." (PMID 34572503, 2021). "Fast-acting insulin aspart, an ultrafast-acting insulin, may be preferred over RAIAs in patients with T2DM for better control of 1-h postprandial hyperglycemia with similar control at 2–4 h." (PMID 34071359, 2021). "In diabetic patients, an altered rate of gluconeogenesis is responsible for increased hepatic glucose output (HGO) and therefore sustained hyperglycemia is observed in both insulin-dependent DM and non-insulin-dependent DM." (PMID 34812979, 2021). "The net effect is a reduction of the insulin demand, but without leading neither to hypo- nor hyperglycemia, again indicating a beneficial effect by reducing the overload of the endocrine pancreas." (PMID 34209137, 2021). "Type 2 diabetes (T2D) is a complicated metabolic condition marked by peripheral insulin resistance, obesity, hyperglycemia, and elevated levels of cytokines, all of which contribute to a lack of insulin and consequent β-cell failure." (PMID 34206537, 2021). "It is characterized by hyperglycemia, where the hormone insulin is either not produced sufficiently or where there is a resistance to insulin." (PMID 33800470, 2021). "Indeed, it has been shown that hyperglycemia upregulates AT1R leading to β-cell function impairment and insulin secretion." (PMID 34124187, 2021). "We demonstrated that recipients of the I-K’s had stable renal function, as well as noted reversal of their hyperglycemia for the duration of the experiment (> 250 days) without need for exogeneous insulin." (PMID 34054721, 2021). "Furthermore, we demonstrate for the first time that PU-MSCs can also reduce hyperglycemia, serum LDL-C levels, and liver lipid deposition and restore insulin sensitivity to an extent similar to that of UC-MSCs." (PMID 34233739, 2021). "Overall, fasting hyperglycemia and increases in body weight were evident at 3 days of high-fat diet without elevations in plasma insulin." (PMID 33868178, 2021). "Two weeks following STZ‐challenge, both WT and KOs exhibited hyperglycemia compared to the vehicle controls although none of the mice reached the threshold requiring insulin dosing." (PMID 34877823, 2021).